SLC7A11 (solute carrier family 7 member 11)
Diseases named in the same sentence as SLC7A11 in open-access papers (continued):
Sharing a sentence is not in itself a finding about the gene and the disease.
tumor (continued). "Cystine/glutamate antiporter solute carrier family 7 member 11 (SLC7A11) is a major transporter regulating cysteine in tumor cells and is induced in response to a variety of stimuli, such as oxidative stress and electrophilic compounds." (PMID 36741694, 2022). "SLC7A11 is generally upregulated in tumour cells, especially those chemotherapy‐ and radiotherapy‐resistant tumour cells." (PMID 35522946, 2022). "Genes blocking ferroptosis were upregulated (e.g., Slc40a1, Slc7a11, Slc3a2, and Gpx4) in Tyro3-OE 4T1 tumor cells, whereas genes that induced or enhanced ferroptosis were downregulated (e.g., Slc5a1 and Tfrc), compared with levels in 4T1-P cells." (PMID 35399527, 2022). "Both drugs can suppress tumor growth by inhibiting the SLC7A11 transporter activity of SLC7A11 and ferroptosis in vivo." (PMID 36552652, 2022). "In this study, using transcriptomic analysis in addition to in vitro and in vivo experiments, we investigate a hitherto unrecognized function of YY2 in tumor cells ferroptosis and tumorigenesis through regulation of SLC7A11‐mediated GSH synthesis." (PMID 35246964, 2022). "They secrete interferon-γ, and then inhibit cystine uptake in tumor cells by down-regulating the expression of ferroptosis-related genes (SLC7A11), thus enhancing ferroptosis in tumors." (PMID 35835721, 2022). "A study has found that SLC7A11 is up regulated in a variety of tumor cells, promotes glutathione (GSH) synthesis to inhibit damage from oxidative stress to tumor cells, and is negatively correlated with the median OS of patients." (PMID 36185243, 2022). "SLC7A11 is overexpressed in various cancers; it promotes glutathione synthesis, providing antioxidant defense for tumor cells by introducing cysteine." (PMID 36274142, 2022). "Strikingly, there are many literature reports confirming that the SLC7A11 gene is closely related to the tumourigenesis, survival, proliferation, metastasis, therapeutic resistance, and other aspects of tumour cells." (PMID 35804831, 2022). "In tumors, knockout of ARID1A impaired transcriptional activation of SLC7A11 and makes tumor cells more sensitive to GSH metabolic pathway inhibitors due to insufficient cysteine supply." (PMID 36399105, 2022). "SLC7A11/xCT is such a target we can utilize in nutrient transporter inhibition-mediated tumor therapy." (PMID 35178349, 2022). "In tumor cells, SLC7A11-mediated cystine uptake promotes GPX4 protein synthesis to reduce sensitivity to ferroptotic cell death." (PMID 36138043, 2022). "The latest research demonstrates that SLC7A11 can enhance tumor development by inhibiting ferroptosis and other ferroptosis-independent functions." (PMID 35721711, 2022). "SLC7A11, a critical regulator of ferroptosis, overexpresses in multiple human cancers to promote tumor growth through suppressing ferroptosis." (PMID 35493518, 2022). "Pharmacologic inhibitors of SLC7A11 effectively induce tumor regression and abrogate MCU-driven metastasis in PDAC." (PMID 36105219, 2022). "Increased expression of SLC7A11 and/or CD44 is found in various human cancers and is closely associated with tumor invasion, lymph node metastasis, recurrence, and poor prognosis." (PMID 36552652, 2022). "Studies showed that the CD44 variant (CD44v), a cell adhesion molecule widely expressed in various CSCs controls the intracellular levels of reduced GSH by directly interacting with the h SLC7A11, thereby promoting tumor growth." (PMID 35566360, 2022). "Recent studies have shown that the IFN γ released by CD8+ T cells downregulates the expression of SLC3A2 and SLC7A11 and impairs the uptake of cystine by tumor cells, thereby promoting lipid peroxidation and ferroptosis in tumor cells." (PMID 36233241, 2022). "Immunohistochemistry staining revealed that while YY2 overexpression induced lipid peroxidation in xenograft tumor lesions, SLC7A11 overexpression suppressed it." (PMID 35246964, 2022).
tumor (continued). "Further, the genetic deletion of SLC7A11 in various preclinical tumor models acts synergistically with immune checkpoint immunotherapeutic agents, such as anti-CTLA4, to suppress tumor growth." (PMID 35065965, 2022). "Several studies had confirmed that when GULT or glutaminase inhibitors were used on tumor cells with high expression of SLC7A11, the mortality of tumor cells was significantly increased, and this effect was independent of the GSH-GPX4 axis." (PMID 36457488, 2022). "qRT-PCR and western blot assays evaluated SNHG3, miR-152-3p, and SLC7A11 levels in tumor tissue, respectively." (PMID 35123415, 2022). "SLC7A11 is widely expressed in various tumor tissues, and plays a significant role in inhibiting ferroptosis during the occurrence and development of tumors by controlling cysteine transport." (PMID 36310600, 2022). "Radiotherapy and immunotherapy enhance lipid oxidation and the ferroptosis of tumor cells by synergistically suppressing SLC7A11." (PMID 35805124, 2022). "The combination of sulfasalazine, an ferroptosis inducer targeting SLC7A11, and IR enhanced the sensitivity of cancer cells to radiotherapy, synergistically induced ferroptosis, and significantly inhibited tumor growth." (PMID 36505465, 2022). "ATF4-dependent tumor promotion is mediated by transcriptional targeting of the glutamate reverse transporter Xc/SLC7A11." (PMID 36430250, 2022). "Together, these results indicated that the regulatory action of YY2 on SLC7A11 was essential for inducing tumor ferroptosis, most likely via suppression of cellular cysteine and GSH levels." (PMID 35246964, 2022). "Specifically, interferon gamma released from CD8+ T cells restrain the synthesis of GSH through downregulating SLC3A2 and SLC7A11, therefore leading to the accumulation of peroxidated phospholipid and ferroptosis in tumor cells." (PMID 35874826, 2022). "Accumulating evidence has shown that the expression of SLC7A11 is fine-tuned at multiple levels, and plays diverse functional and pharmacological roles in tumours, such as cellular redox homeostasis, cell growth and death, and cell metabolism." (PMID 35804831, 2022). "SLC7A11 expression can also be repressed by transcription factors that play a role in tumor suppression." (PMID 36552652, 2022). "IFNγ derived from CD8+ T cells activated by immunotherapy and ATM activated by radiotherapy synergistically inhibit SLC7A11, inducing ferroptosis in tumor cells." (PMID 36072803, 2022). "Immunotherapy-activated CD8+T cells induce tumor cell ferroptotic death by producing IFN in concert with radiotherapy -activated ATM targeting SLC7A11 to inhibit cystine uptake." (PMID 36505465, 2022). "Conversely, downregulation of SLC7A11 impaired tumor sphere formation and sensitized CSCs to doxorubicin treatment." (PMID 35011702, 2022). "T-cell-induced metabolic changes can affect the fate of GBM cells via SLC7A11, and tumour metabolism also promotes immune evasion by inducing SLC7A11-mediated T-cell activation dysfunction." (PMID 35804831, 2022). "Suppression of SLC7A11 significantly inhibited the growth of tumor cells by leading to ferroptosis, while activation of SLC7A11 correlated to tumor progression positively." (PMID 35835852, 2022). "In GBM, RNA binding protein NKAP protects tumor cells from ferroptosis by promoting SLC7A11 mRNA splicing in an m6A-dependent manner." (PMID 36266731, 2022). "Our study suggested that SSZ would be useful to overcome the resistance to ICI by modulating the pro-tumor function of Slc7a11-positive M2-like macrophages." (PMID 36470862, 2022).
tumor (continued). "On the other hand, human tumor cells overexpress SLC7A11, which exhibit greater resistance to ferroptosis and weaken the effect of tumor suppressors." (PMID 36238649, 2022). "In human cancer, ATF4 promotes the transcription of genes involved in stress response, including SLC7A11, to increase tumor angiogenesis and shape blood vessel architecture." (PMID 36552652, 2022). "Levels of the amino acid cystine alone were sufficient to explain these findings, as cystine activated the cystine/glutamate antiporter xCT (SLC7A11) to drive tumor glutamine uptake." (PMID 36203456, 2022). "YY2 mRNA was relatively low in tumor lesions compared to corresponding adjacent tissues; whereas YY1 and SLC7A11 mRNA was upregulated in tumor lesions." (PMID 35246964, 2022). "Membrane-associated progesterone receptor component 1 (PGRMC1) inhibits SLC7A11 through autophagic degradation of lipids and induces ferroptosis in paclitaxel-resistant tumor cells." (PMID 36185243, 2022). "Here, it is determined that YY2 induces tumor cell ferroptosis and subsequently suppresses tumorigenesis by inhibiting solute carrier family 7 member 11 (SLC7A11) transcription, leading to the decreased glutathione biosynthesis." (PMID 35246964, 2022). "SLC7A11 is highly expressed in CAFs, enabling tumor cells to protect against exogenous oxidative stress." (PMID 36552652, 2022). "Recent evidence support that cancer cells upregulate SLC7A11 expression through diverse mechanisms to enhance their antioxidant defence and to suppress ferroptosis, a key tumour suppression mechanism." (PMID 35167614, 2022). "Some authors have demonstrated that SLC7A11 is overexpressed in various types of tumour cells, maintains intracellular redox balance, and inhibits intracellular ROS accumulation and ferroptosis resistance." (PMID 35804831, 2022). "We found that the expression of lncRNA HEPFAL in tumor tissues was significantly lower than that in normal tissues, while SLC7A11 expression was higher in tumor tissues." (PMID 36008384, 2022). "Immunotherapy sensitizes tumors to radiotherapy by promoting tumor-cell ferroptosis and SLC7A11 was a critical regulator in this process." (PMID 36033530, 2022). "Next, functional study indicates that SLC7A11 siRNAs suppress tumour cell growth, and enhance cell death and lipid ROS production, which can be rescued by the ferroptosis inhibitor." (PMID 35415880, 2022). "SLC7A11 also affects the nutritional dependence of tumour cells through glutamine anaplerosis and GLS dependence." (PMID 35804831, 2022). "SLC7A11 is overexpressed in various human cancers and regulates tumor development, proliferation, metastasis, microenvironment, and treatment resistance." (PMID 36552652, 2022). "SLC7A11 acts as a component of the system Xc− cystine/glutamate antiporter, is highly upregulated in human tumours, and can protect cells from lipid peroxidation‐induced ferroptosis." (PMID 35522946, 2022). "Interferon gamma (IFN-γ) secreted by CD8+ T cells downregulates the expression of SLC3A2 and SLC7A11 in tumour cells, impairs the uptake of cystine and, as a consequence, promotes lipid peroxidation and ferroptosis in tumour cells." (PMID 35804831, 2022). "The gene expression level of SLC7A11 was significantly higher in tumor samples than that in normal tissues of COAD in TCGA and GEO databases (p < 0.01)." (PMID 35517862, 2022). "Conversely, suppressing m6A levels via METTL3‐siRNA treatments suppressed SLC7A11 expression, allowing increased accrual of lipid ROS and consequent induced ferroptosis, thus preventing tumorigenesis of HB cancer cells and tumour growth in mice." (PMID 35604883, 2022). "When micronutrient levels are adequate, glutamate provides carbon and nitrogen sources, and SLC7A11-mediated secretion is disadvantageous to support tumour cell proliferation." (PMID 35804831, 2022).
tumor (continued). "IFN-γ down-modulates the expression of SLC3A2 and SLC7A11 and inactivates cystine uptake, in turn promoting lipid peroxidation and ferroptosis in tumor cells and increasing the clinical benefit of cancer immunotherapy." (PMID 36335094, 2022). "SLC7A11, a subunit of system Xc−, was recently shown to be overexpressed in multiple human cancers and to promote tumor progression partly by suppressing ferroptosis." (PMID 34996469, 2022). "A study has shown that ATF4 can stimulate the transcription of SCLS7A11 and promote tumor angiogenesis.Another transcription factor, Nrf2, which promotes SLC7A11 transcription, is a key regulator of antioxidant response." (PMID 36105219, 2022). "Systemic depletion of cystine through cyst(e)inase or genetically knockout of SLC7A11 significantly suppresses tumor growth in leukemia stem cells and genetically-engineered mouse models with chronic lymphocytic leukemia or pancreatic tumor." (PMID 35178349, 2022). "Functionally, the OTUB1-SLC7A11 axis was critical for tumor growth and OTUB1 inactivation promotes ferroptosis in human cancer cells primarily by down-regulating SLC7A11 levels." (PMID 35307036, 2022). "Inhibition of Slc7a11 with sulfasalazine inhibited the pro-tumor function of M2-like macrophages and synergized with anti-PD1 antibody." (PMID 36470862, 2022). "In HCC, erastin has been verified to have anti-tumor effects, and SLC7A11 is closely related to the occurrence and development of HCC." (PMID 36008384, 2022). "According to recent research, SLC7A11 overexpression promotes tumor development by impeding ferroptosis." (PMID 36267158, 2022). "The results showed that the overexpression of SLC7A11 inhibited the ferroptosis of tumor cells and promoted the development and metastasis of COAD." (PMID 35517862, 2022). "Overexpression of SLC7A11 promotes tumor development via suppressing oxidative stress-induced ferroptosis and non-ferroptotic cell death." (PMID 35053507, 2022). "The researchers suggested that IR also induces adaptive responses involving SLC7A11 or GPX4 induction to promote tumor cell survival during radiotherapy, which is one of the reasons for radioresistance." (PMID 36072803, 2022). "SLC7A11 inhibition in MCU-high PDAC effectively induces tumor regression and abolishes MCU-driven metastasis." (PMID 36552652, 2022). "FTO is able to inhibit the occurrence of PTC by downregulating SLC7A11 in m6A independently, and it functions as a tumor suppressor gene in PTC." (PMID 35721711, 2022). "A study with genetically engineered mice has found that the deletion of SLC7A11 can induce tumor-selective ferroptosis and the inhibition of PDAC growth." (PMID 36499358, 2022). "In support of this notion, SLC7A11 is often overexpressed in a variety of tumour cells including HB." (PMID 35415880, 2022). "In conclusion, we identified YY2 as a novel regulator of ferroptosis in tumor cells, which acted through the SLC7A11/GSH synthesis axis." (PMID 35246964, 2022). "Many reports have suggested that the inhibition of SLC7A11 expression and activity is favourable for tumour therapy; thus, SLC7A11 is regarded as a potential therapeutic target." (PMID 35804831, 2022).
tumor (continued). "A likely beneficial approach would be to screen patient tumours for low SLC7A11 expression, as high expression of SLC7A11 correlates with resistance to ferroptosis inducers." (PMID 34205617, 2021). "The multivariate model showed that NRF2 nuclear expression and SLC7A11 expression, sex and tumor location are independent prognostic factors." (PMID 34446045, 2021). "Collectively, these studies suggest that administration of compounds targeting SLC7A11 to promote RT-induced ferroptosis is likely a promising strategy for radiosensitization in vivo, which is in line with other studies targeting SLC7A11 for tumor suppression." (PMID 33891303, 2021). "A CD44 variant (CD44v) interacts with and stabilizes SLC7A11 at the plasma membrane, and therefore positively regulates the GSH levels and ROS scavenging in tumor cells, and in particular, in CD44-expressing colorectal and gastrointestinal CSCs." (PMID 33401748, 2021). "It is biologically plausible that tumor cells upregulate SLC7A11 expression to shirk ferroptosis execution and further undermine patients’ survival." (PMID 34938318, 2021). "We will then discuss how SLC7A11 promotes tumor development through its function in inhibiting ferroptosis as well as other ferroptosis-independent functions." (PMID 33000412, 2021). "Due to the insufficiency of normal samples in some tumor categories in TCGA, we further incorporated the transcriptome data from GTEx and re-evaluated the differential expression of SLC7A11 in 27 cancers." (PMID 34938318, 2021). "Recent studies revealed that SLC7A11 overexpression promotes tumor growth partly through suppressing ferroptosis." (PMID 34722314, 2021). "Further, immunohistochemical analysis of HCC tumor sections revealed that SLC7A11 was upregulated in HCC of patients as compared with adjacent liver parenchyma." (PMID 34664408, 2021). "Using ferroptosis inducers or agonists targeting SLC7A11 has the potential to sensitize radioresistant tumor cells." (PMID 34249928, 2021). "In line with this, an approach to block SLC7A11 impairs glutamate/cystine exchange in tumour cells but with only a moderate influence on T cell function." (PMID 34541580, 2021). "In oral squamous cell carcinoma (OSCC), miR-375 acts as a tumor suppressor by inhibiting SLC7A11 expression, leading to ferroptosis." (PMID 34235152, 2021). "On the other hand, moderate and strong staining patterns for CD44, DPP4, and SLC7A11 were observed in the cytoplasm and cell membrane of tumor tissues, while NCOA4 only exhibited weak positive staining on the cell membrane of tumor tissues." (PMID 34370716, 2021). "In cancer cells, not only de-repression of SLC7A11 expression, but also stabilization of SLC7A11 protein can lead to enhanced tumor formation through inhibiting ferroptosis." (PMID 33000412, 2021). "SLC7A11 has been reported to be involved in tumor progression, but its correlation with drug resistance in OC was poorly understood." (PMID 34790572, 2021). "This review will provide the foundation for further understanding SLC7A11 in ferroptosis, nutrient dependency, and tumor biology and for developing novel effective cancer therapies." (PMID 33000412, 2021).